CSF1R (colony stimulating factor 1 receptor)
Diseases named in the same sentence as CSF1R in open-access papers (continued):
Sharing a sentence is not in itself a finding about the gene and the disease.
glioma (144 papers, 2013 to 2025). A benign or malignant brain and spinal cord tumor that arises from glial cells (astrocytes, oligodendrocytes, ependymal cells). "One such approach is inhibiting CSF-1R, a signaling loop that has been implicated in glioma invasion (Section 3.1.2)." (PMID 38893093, 2024). "Several experiments were performed to target glioma-associated macrophage populations by colony-stimulating factor-1 receptor (CSF-1R)." (PMID 36762114, 2023). "Although these findings suggest that CSF-1 and IL-34 are susceptible to regulation, anti-CSF-1R therapy warrants further study for effective use in glioma treatment." (PMID 37153567, 2023). "The tumor microenvironment underlies acquired resistance to colony stimulating factor-1 receptor inhibition in gliomas." (PMID 37867521, 2023). "We demonstrated that CSF-1R inhibition affects both glioma cells and specific glioma-associated myeloid-derived cell populations." (PMID 35115369, 2022). "QUESTION: Is 18F-DPA-714 PET suitable to decipher glioma-associated immune cell dynamics and CSF-1R therapy outcomes?" (PMID 35115369, 2022). "Small-molecule CSF-1R inhibitors are used to study the dynamics of these cells in glioma progression and glioma-associated inflammation, profiting from their ability to modulate GAMMs through a mechanism of depletion and repopulation." (PMID 35115369, 2022). "It was previously shown by our laboratory that tumor-associated microglia (TAMs) stimulate glioma cell invasion and this process is dependent on CSF-1R signaling." (PMID 34843542, 2021). "In the context of a high-grade brain tumor model where glioma-associated macrophages/microglia (GAMs) were M2 polarized, CSF1R inhibitors were found to decrease expression of M2 markers in GAMs such as Arg1 and Mrc1 (CD206) without influencing their numbers." (PMID 34281564, 2021). "Based on our results so far, we concluded that anti-CSF1R antibodies reshape the glioma-associated microenvironment by decreasing CD204+ cells and increasing the influx of CD8+ cells." (PMID 34063518, 2021). "Since PI3K signaling was shown to contribute to M2-polarization of these tumor associated macrophages (TAMs) and PI3K binding to CSF1R was shown to enhance spreading of macrophages, thus promoting glioma cell invasion." (PMID 31009513, 2019). "The “re-education” or depletion of tumor-associated microglia and macrophages by colony-stimulating factor 1 receptor (CSF1R) inhibition significantly reduces glioma progression." (PMID 30972297, 2019). "Involvement of CSF1R in certain types of cancers, such as gliomas, also correlates with poor disease prognosis, as proliferation of CSF1R-controlled tumor-associated macrophages (TAMs) correlates with tumor angiogenesis and metastasis." (PMID 30551596, 2018). "Our findings suggest that high-risk score gliomas may drive an immunosuppressive microenvironment via the CSF1R-macrophage axis, thereby restricting the anti-tumor functionality of CD8+ T cells and, ultimately, leading to resistance to ICB therapy." (PMID 40429753, 2025). "Tumor-associated microglia promoting glioma cell invasion can be mediated by CSF-1R signaling on gliomas, a pathway involving CSF-1 signaling via ERK that upregulates the expression of dual-regulatory proteins (AREG) in microglia, which are ligands for epithelial growth factor receptor (EGFR)." (PMID 37700840, 2023). "Additionally, CSF1R is also on tumor-associated macrophages and microglia (TAMs) which are highly available in glioma microenvironment." (PMID 31527881, 2019). "Finally, we demonstrated that CSF-1R inhibitor treatment was able to prevent fWBI-induced memory loss in glioma bearing animals." (PMID 30421720, 2018). "Glioma-associated microglia and bone-marrow-derived macrophages account for up to 40% of tumour cellularity and display a transcriptional convergence on colony-stimulating-factor-1 receptor (CSF1R)– and PI3Kγ-dependent pathways that promote STAT3 activation, efferocytosis and matrix remodelling." (PMID 40995359, 2025).
glioma (continued). "Therefore, based on the pathways and mechanistic study findings in murine gliomas, it is of clinical importance to detect prognostic signatures based on DEGs and associated pathways that underlie the effect of CSF-1R inhibition among RT-treated LGG patients to optimize novel therapeutic strategies." (PMID 38474320, 2024). "The results indicated that combination therapy of RT with CSF-1R inhibition therapy can target and stabilize these pathways, which were elevated in the RT-only therapy and should reflect the underlying mechanism leading to improved survival of glioma mice and human patients." (PMID 38474320, 2024). "In a PDGFB-driven glioma model, CSF-1R blockade inhibited tumor growth and improved mouse survival by re-programming GAMs rather than causing their depletion." (PMID 40642066, 2025). "As shown by several preclinical and clinical studies, CSF1R in combination with anti-PD1 significantly improves the objective remission rates in patients with solid tumors such as glioma, melanoma, urinary bladder cancer, and non-small cell lung cancer." (PMID 39780291, 2025). "Previous studies have suggested that CSF-1R mutation (e.g., G795A) in macrophages or IGF-1R/PI3K in PDG glioma cells contribute to resistance to CSF-1R inhibitors." (PMID 41365876, 2025). "The results revealed that CSF1R, TGFBI, and IDO1 serve as key nodes in the protein interaction network, suggesting their critical roles in glioma progression and tumor-associated inflammation." (PMID 40881678, 2025). "To conclude our study on TAM-targeted therapies for glioma treatment, we evaluated the application of a CSF-1R inhibitor." (PMID 40845580, 2025). "For instance, the small molecule CSF1R inhibitor BLZ945 blocked the progression of glioma in preclinical models, and the anti-CSF1R antibody RG7155 reduced tumor burden in patients with diffuse-type giant cell tumors." (PMID 39939179, 2025). "Nevertheless, a subsequent study indicated that persistent inhibition of CSF-1R alone was inadequate for long-term tumor control due to drug resistance, and glioma growth resumed after an initial period of slow proliferation." (PMID 38474320, 2024). "One study showed that radiotherapy promoted the accumulation of M‐2‐like macrophages and that a combination of radiotherapy and macrophage inhibition (using CSF‐1R) delayed glioma recurrence." (PMID 38470096, 2024). "There is an urgent need to conduct a translational study to investigate existing evidence for the potential effectiveness of combinations of radiotherapy (RT) plus immunotherapy via CSF-1R inhibition on multiple independent cohorts of human glioma patients." (PMID 38474320, 2024). "Nonetheless, when recurrent tumor cells were isolated and transplanted into naive animals, they observed that gliomas regained sensitivity to CSF-1R inhibition, suggesting that resistance to CSF-1R inhibition is driven by the TME." (PMID 39457693, 2024). "CSF-1R-overexpressing glioma cells showed increased cell viability, ki-67-positivity and enhanced colony forming ability." (PMID 38254773, 2024). "Several studies have indicated that targeting MGs via CSF1R inhibition can delay recurrence and extend overall survival in several glioma models by inducing a more pro-inflammatory phenotype in immune cells." (PMID 38665919, 2024). "Further, CSF1R inhibitors (GW2580) reduce myeloid cells in the tumor microenvironment of gliomas and significantly decrease the expression of chemokine CXCL7, thus inhibiting tumor growth." (PMID 38671536, 2024). "The most statistically significant signaling pathway in the KEGG enrichment analysis is the PI3K/AKT pathway, which is of critical importance in CSF-1R inhibition or radiation therapy in mouse glioma models." (PMID 38474320, 2024). "Recent mechanistic studies have indicated that combinations of radiotherapy (RT) plus immunotherapy (via CSF-1R inhibition) can serve as a strategy to overcome RT resistance and improve the survival of glioma mice." (PMID 38474320, 2024).
glioma (continued). "If differentiation is occurring within the glioma, post-monocyte extravasation, then CSF1R-targeting agents would be most effective if they cross the BBB." (PMID 39272914, 2024). "We began with the experimental findings of a preclinical mouse study that revealed CSF-1R inhibition as a useful strategy to overcome radiation resistance in murine gliomas." (PMID 38474320, 2024). "Of note, CSF-1R inhibition induced MΦ repolarization to an anti-tumor phenotype and blocked tumor progression in a mouse glioma model." (PMID 39596395, 2024). "Glioma-derived CSF-1 not only acts as chemoattractant but also induces a shift of microglia and macrophages toward a pro-tumor phenotype, and blocking CSF-1 receptor (CSF-1R) inhibits alternative activation of TAMs and attenuates glioma progression." (PMID 38254796, 2024). "In xenograft and transgenic murine models, the inhibition of CSF-1R was shown to halt glioma progression and growth." (PMID 38893093, 2024). "Most interesting, a new phase I study using SYHA1813, a VEGFR and CSF1R dual inhibitor, has been reported to show anti-tumor activity in patients with recurrent High-Grade Gliomas and Advanced Solid Tumors." (PMID 38665919, 2024). "For instance, in the context of gliomas, the combination of CSF1R inhibitors and radiotherapy has shown synergistic results by effectively suppressing tumor growth." (PMID 38665919, 2024). "This implication is supported by results from an animal model in which CSF-1R is blocked, thereby affecting their functional polarization and blocking their glioma progression." (PMID 38791312, 2024). "The involvement of the CSF-1R in CNS tumors, including glioma and glioblastoma, has been extensively reviewed." (PMID 39457693, 2024). "CSF-1 Receptor (CSF1R) is critical in macrophage differentiation and survival, and inhibition of this pathway in GBM mouse models has shown glioma regression through polarization of tumor associated macrophages (TAM) towards an inflammatory phenotype." (PMID 39346924, 2024). "From these mouse data and Cox model results, it is reasonable to expect that the combination of radiotherapy and CSF-1R inhibition therapy can improve survival in human glioma patients." (PMID 38474320, 2024). "Blocking CSF1‐R in glioma‐bearing mice led to a reduced infiltration of GAMs and decreased tumor volume significantly." (PMID 37849438, 2023). "CSF1R is an interesting target because it is overexpressed in HGG; and its levels are associated with glioma grade, and high CSF1R levels are associated with poor clinical outcomes." (PMID 36884148, 2023). "Although administration of anti-CSF-1R therapy to glioma experimental animals exhibited an excellent initial reaction, nearly half of experimental animals eventually developed drug resistance and tumor recurrence." (PMID 37153567, 2023). "We previously demonstrated that inhibition of TAM infiltration into glioma tumors with the CSF-1R antagonist pexidartinib (PLX3397) can inhibit glioma cell invasion in-vitro and in-vivo." (PMID 36982211, 2023). "CSF-1 secreted by glioma cells acts on CSF-1R on microglia, which attracts microglia to the tumor and induces a shift to a pro-tumorigenic phenotype, enhancing the crosstalk between microglia and glioma." (PMID 37700840, 2023). "OV treatment regimens, engineered microglia and some potential agents (CSF-1R inhibitor, Flavonoids, Arginine-depleting agents) can also be considered as a new attempt to treat glioma." (PMID 37700840, 2023). "PLX3397 (another CSF-1R inhibitor) markedly suppresses glioma cell proliferation and invasion and reduces the grade of malignancy in a PDGF-B-driven proneural glioma mouse model." (PMID 37705736, 2023). "Experimental studies have revealed a macrophage-mediated drug resistance mechanism in which the TME undergoes adaptation in response to macrophage-targeted CSF1R inhibition therapy in gliomas." (PMID 37190507, 2023).
glioma (continued). "Treatment with the anti-CSF-1R antibody pexidartinib (PLX3397) significantly reduces GL261-associated GAM infiltration and inhibits M2 polarization, thereby inhibiting glioma growth." (PMID 36969167, 2023). "One such approach targets the colony-stimulating factor 1 receptor (CSF1R) because glioma cells produce the ligand cytokines CSF1 and IL34 abundantly, which act on GAMs through CSF1R." (PMID 36968288, 2023). "In mice, inhibition of CSF-1R can either block the transformation of M2 macrophages or deplete TAMs to prevent glioma progression and invasion." (PMID 36762114, 2023). "These glioma‐supplied cytokines were also responsible for changing the transcriptomic profile of surviving TAMs, reprogramming them toward a less pro‐tumoral phenotype by reducing the polarization of M2 macrophages in gliomas treated with CSF‐1R inhibitor." (PMID 36684102, 2023). "While CSF-1R, CSF-1 and IL-34 directly support tumor cell growth, CSF-1, highly expressed by glioma cells, effectively promotes macrophage recruitment and indirectly promotes malignant pathogenesis via GAM interactions." (PMID 37153567, 2023). "A previous study showed that colony-stimulating factor 1 receptor inhibition alters macrophage polarization and blocks glioma progression." (PMID 36747161, 2023). "We have previously shown that the CSF-1/CSF-1R axis is critical for microglia stimulated glioma invasion using both the coculture in-vitro assay and using syngeneic C57BL/6 mouse model." (PMID 36982211, 2023). "Colony-stimulating factor 1 receptor (CSF-1R) was found to inhibit macrophage polarization and block glioma progression." (PMID 36712881, 2022). "BLZ945, a small-molecule CSF1R inhibitor, has been shown to ameliorate glioma progression by educating TAMs into an anti-tumor phenotype in a PN mouse model of GBM." (PMID 35600367, 2022). "Altogether, these findings provide new insight into CSF-1R therapy resistance in glioma and identify novel therapeutic glioma targets." (PMID 35115369, 2022). "Conclusion:18F-FET and 18F-DPA-714 PET/MRI allow noninvasive assessment of glioma growth under various regimens of CSF-1R therapy." (PMID 35115369, 2022). "A previous study proved that CSF-1R inhibition altered macrophage polarization and blocked glioma progression." (PMID 35260161, 2022). "After repopulation, CSF-1R signal remained reduced and CSF-1R+ cells were visible at the periphery of the glioma." (PMID 35115369, 2022). "In this regard, a short-term (1 wk) CSF-1R inhibition with subsequent brain repopulation during glioma progression led to a significant reduction in tumor volume as quantified by both gadolinium-enhanced MRI and 18F-FET PET." (PMID 35115369, 2022). "CSF-1R inhibitors are known to deplete or polarize TAMs, leading to the suppression of glioma progression." (PMID 35203505, 2022). "CSF-1 released from glioma cells functions as a chemo-attractant, and CSF-1R antagonist reduced the infiltration of TAMs and ameliorated glioblastoma invasion in vivo." (PMID 35600367, 2022). "In light of these divergent effects of CSF1R-inhibition in different glioma models and therapeutic settings, it will be important in the future to define mechanisms behind tumor-type-specific actions of CSF1R-inhibition." (PMID 35267626, 2022). "Radiotherapy was previously shown to increase the therapeutic effect of CSF1R-inhibition in a PDGF-driven glioma model and thus justifies clinical translation." (PMID 35267626, 2022). "PLX5622 treatment reduced CSF-1R expression, with few CSF-1R+, Iba1+ cells present at the border of the glioma." (PMID 35115369, 2022). "Our results show the efficacy of CSF-1R inhibition for the blockade of GAMM proliferation and that the combination of 18F-FET and 18F-DPA-714 PET can be used to monitor CSF-1R therapy–induced changes in the glioma microenvironment." (PMID 35115369, 2022).
glioma (continued). "Blockade of CSF-1R signaling by using the PLX3397 (a CSF-1R inhibitor) in glioma-bearing mice decreased the recruitment of TAMs and reduced the GBM invasion." (PMID 35967394, 2022). "Those persistent cells were present within and at the periphery of the glioma and showed reduced CSF-1R and TSPO expression compared with the preconditioned-and-repopulated group; few of the cells expressed both markers." (PMID 35115369, 2022). "In Gl261 murine glioma, which is also sensitive to anti-CSF1R treatment, CSF1R-inhibition leads to TAM depletion with a more pronounced effect on the microglial fraction compared to macrophages." (PMID 35267626, 2022). "Gliomas treated with a tripartite regimen (DC vaccine, PD-1 monoclonal antibody, and colony-stimulating factor 1 receptor inhibitor (PLX3397)) had included survival in vivo." (PMID 39280892, 2022). "To study the impact of CD44-positive myeloid cells on glioma growth and progression in vivo, we carried out intracranial orthotopic injections in CD44fl/fl (floxed) and Csf1r-Cre/CD44fl/fl conditional knockout (cKO) mice." (PMID 35992852, 2022). "In models of glioma, macrophage inhibition through targeting Colony Stimulating Factor-1 Receptor (CSF-1R) decreases tumour volume." (PMID 35359423, 2022). "Colony-stimulating factor-1 (CSF-1) is able promote the function and survival of small glioma cells and TAMs, and the inhibition of the CSF-1 receptor (CSF-1R) relieves TME immunosuppression by depleting TAMs and synergizes with other immunotherapies." (PMID 35833121, 2022). "In fact, CSF1R inhibition as a treatment of glioma is being evaluated in some early-phase human clinical trials." (PMID 35800363, 2022). "Some receptors such as the colony-stimulating growth factor receptor-1 (CSF-1R) can activate these macro-phages and constitute new targets for glioma." (PMID 36555334, 2022). "In vivo, however, CSF-1R inhibitor only depleted microglia in the adjacent normal brain but not GAMs within proneural glioblastoma xenografts and murine gliomas." (PMID 33803414, 2021). "Attempts have been made to pharmacologically reduce TAMs in glioma, for example with CSF-1R inhibitors that decreased M2-like TAMs and increased survival in mouse transgenic and human xenograft glioblastoma models." (PMID 33564072, 2021). "We previously published that microglial-stimulation of glioma invasion was almost completely inhibited by pharmacological inhibition of the CSF-1 receptor (CSF-1R)." (PMID 34843542, 2021). "Treatment with a CSF-1R inhibitor slowed the intracranial growth of patient-derived glioma xenografts." (PMID 33809675, 2021). "BLZ945, a blocker of CSF-1R, was found to downregulate the expression of the M2 phenotype of TAMs and restrict glioma growth." (PMID 34439380, 2021). "In glioma models, CSF-1R inhibition delays recurrence and slightly prolonged overall survival by altering the immune cell polarization state toward a less immunosuppressive phenotype." (PMID 34950148, 2021). "In experimental glioma models, CSF-1R inhibition significantly prolonged overall survival while recurrence was observed in a considerable subset of animals." (PMID 34950148, 2021). "In glioma, CSF-1R inhibition was combined with ionizing radiation and potentiated the response of the tumour to irradiation, indicated by decreased irradiation-induced monocytes recruitment, reduced pro-tumorigenic TAMs and longer survival." (PMID 34950148, 2021). "In both glioma and ischemia, a resistant population of CSF-1R-independent microglia/macrophages were observed after long-term PLX5622 treatment." (PMID 34950148, 2021). "High levels of CSF-1 and CSF-1R have been observed in high-grade human glioma, supporting their pivotal role in tumour growth." (PMID 34950148, 2021). "We have previously shown that microglia stimulate invasion of murine and human glioma cell lines and this is dependent on CSF-1R and EGFR signaling in a putative paracrine interaction." (PMID 34843542, 2021).